CYP17A1 (cytochrome P450 family 17 subfamily A member 1)
Diseases named in the same sentence as CYP17A1 in open-access papers (continued):
Sharing a sentence is not in itself a finding about the gene and the disease.
tumor (continued). "In contrast, VCaP xenografts harvested after only 8 days of abiraterone (0.5 mg/day every other day by intraperitoneal injection) showed no change in CYP17A1 mRNA expression compared to pre-treatment tumor samples." (PMID 27487144, 2016). "In contrast to all other cell models the AR-negative, malignant tumour cell line PC-3 treated with AA does not show any significant effects on CYP17A1 and AKR1C3 expression." (PMID 25332874, 2014). "The CYP17A1 up-regulation under AA is not restricted to tumour cells but is elicited when AR signaling is impaired." (PMID 25332874, 2014). "Although their exact mechanism of action in controlling tumor growth is not known, EDCs may inhibit steroidogenic enzymes such as CYP17A1 or CYP19A1 which are involved in the production of androgens or estrogens." (PMID 38397440, 2024). "CYP17A1 is an enzyme important in the synthesis of dihydrotestosterone (DHT) from cholesterol and may be targeted in the testes, adrenal glands, and prostate to reduce tumor burden in PCa." (PMID 26909338, 2016). "The median CYP11A1 mRNA level in the CRPC metastases was 0.41 times compared to the level in the primary tumor tissue (P = 0.011), while the CYP17A1 and HSD3B2 mRNA levels in CRPC bone metastases were not significantly different from levels in the primary tumor tissue." (PMID 24244276, 2013). "It is possible that Lathyrol may influence the expression of CYP17A1 and PARP1, thereby affecting the synthesis and phosphorylation of AR, then produce negative results to the function and activity of neoplasm cells." (PMID 38965120, 2024).
cancer (33 papers, 2002 to 2026). A tumor composed of atypical neoplastic, often pleomorphic cells that invade other tissues. "In this meta-analysis, we systematically reviewed and synthesized data from 29 studies to assess the CYP17A1 rs743572 polymorphism’s relationship with cancer susceptibility." (PMID 40561159, 2025). "The role of the CYP17A1 gene’s rs743572 polymorphism in cancer susceptibility has been a subject of extensive investigation, yet existing evidence remains inconclusive." (PMID 40561159, 2025). "Missense/LoF variants in CYP17A1 have been shown to cause fertility impairments and related cancers." (PMID 40182431, 2025). "Among these enzymes, CYP17A1, belonging to the cytochrome P450 family, is particularly pivotal for human health and its association with cancer." (PMID 40561159, 2025). "CYP17A1 belongs to the cytochrome p450 family and is involved in the metabolism of endogenous compounds and sex hormones and has been associated with cancers." (PMID 28508326, 2018). "Meta-analysis of CYP17A1 rs743572 polymorphism’s association with cancer risk." (PMID 40561159, 2025). "FPRP values for CYP17A1 rs743572 polymorphism’s association with cancer risk." (PMID 40561159, 2025). "The dysregulation of these hormones contributes to developing and facilitating diverse cancers, and CYP17A1 emerges as a crucial player in this context." (PMID 40561159, 2025). "CYP17A1 is crucial for intricate cancer biology, particularly in relation to hormone-dependent cancers." (PMID 40561159, 2025). "While the inhibition of CYP17A1 presents a promising approach in certain cancer types, it is essential to consider potential side effects and the broader impact on steroid hormone balance in the body." (PMID 40561159, 2025). "Understanding the intricate relationship between cytochrome P450 enzymes, particularly CYP17A1, and cancer provides valuable insights into the development of targeted therapies aimed at modulating steroid hormone levels." (PMID 40561159, 2025). "Molecular docking revealed stronginteractions of sarcorine C and salonine C with key cancer-associatedproteins (CDK2, KRAS, CYP17A1, Bcl-2, MMP-2, and NOS)." (PMID 41141772, 2025). "These include either the specific upregulation of CYP17A1 or the overexpression of androgen receptors (AR) by cancer cells." (PMID 34579444, 2021). "Since many anti-cancer drugs target enzymes from the steroidogenic pathway, we tested the effect of curcuminoids on cytochrome P450 CYP17A1, CYP21A2, and CYP19A1 enzyme activities." (PMID 31533365, 2019). "Our study has shown a high level of miR-320a-3p in the carcinoma-derived H295R cell line and its potency as a CYP17A1 regulator." (PMID 28852406, 2017). "In our study, we found a significant association between CYP17A1 rs743572 polymorphism with both hormone-sensitive and non-hormone-sensitive cancers, reflecting its dual role in steroid hormone synthesis and broader metabolic pathways." (PMID 40561159, 2025). "By unraveling the molecular mechanisms underlying these processes, researchers strive to devise innovative strategies to mitigate the impact of dysregulated CYP17A1 activity on cancer progression, contributing to advancements in cancer treatment and improving overall human health." (PMID 40561159, 2025). "This exclusion comprised three articles that did not address the association between CYP17A1 rs743572 polymorphism and cancer susceptibility, two review articles, and three that lacked detailed genotyping data." (PMID 40561159, 2025). "The drugs, which received FDA approval for cancer treatment since 2011, inhibit the catalytic activity of such enzymes as steroid 17alpha-monooxygenase (CYP17A1), poly (ADP-ribose) polymerases (PARPs), thymidylate synthase (TS), topoisomerase (TOP) and enhancer of zeste homolog 2 (EZH2)." (PMID 35408658, 2022). "The CYP17A1 gene was amplified less than 1% in all cancer types analyzed." (PMID 31060224, 2019).
cancer (continued). "As a cytochrome P450 17A1 (CYP17A1) inhibitor, abiraterone impedes the production of androgens in adrenal glands, cancer cells and other sources, whilst enzalutamide directly binds to the AR and blocks nuclear translocation and activation of downstream AR-related pathways." (PMID 28241429, 2017). "Thus, CYP17A1 is a druggable target for anti-cancer molecule development." (PMID 36838665, 2023). "Altogether, HSD3B1, HSD3B2, CYP11A1, CYP11B1, CYP17A1, and CYP3A43, hereby defined as APUC-6, demonstrated tissue- and cancer stage–specific interactions, with the most notable interaction in metastatic PC." (PMID 39207857, 2024). "The cancer cells of both CRPC and CSPC express CYP17A1, which is essential for the synthesis of androgen from pregnenolone and progesterone." (PMID 36430730, 2022). "CYP17A1 can maintain intratumor androgen levels that are sufficient enough to reactivate AR signaling in CRPC and promote the resurgent growth of the cancer lesion." (PMID 36430730, 2022). "These qPCR results confirmed a similar distribution of gene expression; overexpression of CYP1B1, CYP7A1, CYP17A1, and CYP19A1, and repression of CYP1A2, CYP2B6, CYP2C19, and CYP26A1 was observed in cancer tissues." (PMID 31258835, 2019). "CYP17A1, as well as CYP19A1, is targeted by inhibitors in cancer treatments." (PMID 36557005, 2022).
metabolic disorders (5 papers, 2015 to 2025). "Finally, although governed physiologically by prandial changes in bile acids levels, the ability of hepatic Cyp17a1 to modify lipid and glucose-handling targets it for potential future intervention in metabolic disease." (PMID 31767173, 2019). "Novel compounds that are safe and non-toxic are needed to target CYP17A1 and CYP19A1 activities to treat metabolic disorders resulting from excess production of androgens or estrogens." (PMID 31533365, 2019).
cardiovascular disorder (3 papers, 2017 to 2020). A disease involving the cardiovascular system. "Rs1004467, which is in the intron region of CYP17A1, has been associated with cardiovascular diseases." (PMID 29942286, 2018).
infection (3 papers, 2009 to 2017). The state of being infected such as from the introduction of a foreign agent such as serum, vaccine, antigenic substance or organism. "The mRNA expression of CYP17A1 decreased, in keeping with the decrease in P4 production in B.suis.S2-infected GTCs at 12 h post-infection." (PMID 26904517, 2016). "The expression of StAR and HSD3B decreased before 24 h post-infection, which was roughly accompanied with decreases in CYP17A1 mRNA expression and P4 production in B.suis.S2-infected cells." (PMID 26904517, 2016).
CYP17A1 also shares sentences with these, for which no sentence is quoted: Hypokalemia (16 papers); cryptorchidism (4); peripheral neuropathy (4); Primary amenorrhea (4); essential hypertension (3); benign prostate hyperplasia (2); bladder cancer (2); Cowden syndrome (2); endometrial cancer (2); fatty liver (2); hepatocellular carcinoma (2); Klinefelter syndrome (2); male breast carcinoma (2); male pattern baldness (2); myocardial infarction (2); peripheral nerve injury (2); seminoma (2); thymoma (2); type 2 diabetes mellitus (2); 3-beta hydroxysteroid dehydrogenase deficiency (1); Addison's disease (1); adrenal gland carcinoma (1); Adrenal Hyperandrogenism (1); adrenal tumors (1); amenorrhea (1); astrocytoma (1); atrial fibrillation (1); autoimmune polyglandular syndrome type-1 (1); Breast Invasive Carcinoma (1); breast tumor (1).
A further 62 diseases each share a sentence with CYP17A1 in 1 paper.